CLDN1 (claudin 1)
Diseases named in the same sentence as CLDN1 in open-access papers (continued):
Sharing a sentence is not in itself a finding about the gene and the disease.
cancer (continued). "CLDN-1 is also involved in Wnt and Notch signaling, which has a significant role in the tumorigenesis, and resistance of cancer cells toward chemotherapeutic drugs." (PMID 39003454, 2024). "The addition of CLDN1 into the viral genome would result in the release of CLDN1 as cancer antigens upon oncolysis, encouraging cancer recognition as CLDN1 is an easily identifiable surface protein." (PMID 39309012, 2024). "Combining miRNA-199-5p with anti-PD-L1 agents improves anti-cancer therapy’s efficacy by downregulating claudin-1." (PMID 39458944, 2024). "Claudin-1 also modulates the genetic profile of LUAD cancer cells by promoting the expression of metastasis suppressors and blunting that of metastasis promotors." (PMID 39364319, 2024). "Claudin-1 is a tight junction protein that has shown promising results in the prognosis and management of cancer in general." (PMID 37102018, 2023). "Cancers with MSI were characterized by downregulation of claudin 1, claudin 3, and claudin 4 and upregulation of claudin 7 and occludin." (PMID 37998722, 2023). "In cancer cells, in addition to being a component of tight junctions, Claudin also plays other roles and is involved in acellular division or invasion, among which Claudin-1 has the greatest potential in the diagnosis and prognosis of many types of cancer." (PMID 36992837, 2023). "Despite being the most studied claudin in cancers to date, the role of CLDN1 in cancer progression is controversial and has been a subject of discussion in cancer research." (PMID 37318881, 2023). "Our results suggest a correlation in the expression levels of claudin-1 in TNBC and clinical surrogates of carcinogenesis and cancer progression, thus this study makes the case for a claudin-1 high subset in TNBC patients." (PMID 37102018, 2023). "We further showed the benefit of a sequential combination of a chemotherapeutic agent such as oxaliplatin with an anti-CLDN1-ADC based on the “one-two punch” strategy to treat patients with chemo-resistant cancer." (PMID 37041570, 2023). "Another proposed mechanism by which CLDN1 regulates cancer metastasis is by its functional role in cellular transformation." (PMID 37318881, 2023). "Specifically, the epithelial markers E-cadherin and claudin 1 were downregulated in platelet-treated cancer cells, whereas snail, vimentin, fibrin, and plasminogen activator inhibitor-1 were upregulated." (PMID 37601099, 2023). "Since CLDN4Y197 and CLDN6Y200 are conserved in human and mouse CLDN1/2/5/9/17/18, it would be interesting to determine the biological significance of the corresponding tyrosine residues in various types of cancer." (PMID 37059993, 2023). "Claudin 1 expression was also attenuated in aggressive carcinomas with unfavorable clinical outcomes among prostatic and lung adenocarcinomas." (PMID 36714681, 2023). "In the present study, we aimed to identify the role of CLDN1 expression on “claudin-1-low” TNBC cancer cell response to chemotherapy." (PMID 36291810, 2022). "We also previously reported that an anti-cancer drug (Δ2-TGZ) induced apoptosis differently in both cell lines: CLDN1 is involved in Δ2-TGZ apoptotic effect in MDA-MB-231 cells but not in Hs578T cells." (PMID 36291810, 2022). "We further demonstrate that C/EBPB governs cancer stemness through the modulation of CLDN1 and LCN2." (PMID 35013251, 2022). "Claudin-1 has also been found to mediate interactions between cancer cells and brain endothelial cells, such as those occurring in TJs, and consequently inhibit transmigration." (PMID 34354941, 2021). "Numerous studies reported that claudin-1 play a significant role in this type of cancer and its elevated expression is observed in most oral, carcinomas." (PMID 34822542, 2021). "Our functional assessment of CLDN1 in cancer cell proliferation, migration, spheroid formation, and wound healing also suggests that elevated CLDN1 expression is associated with a more aggressive phenotype." (PMID 33828978, 2021).
cancer (continued). "In contrast, cancer cells can induce transmigration of endothelial cells to successfully metastasize when claudin-1 is lost on circulating lung endothelial cells." (PMID 34354941, 2021). "The four genes selected through our process which are dysregulated along with CLDN1 and CLDN7 (PIK3CA, SLC6A6, ASAP1, and TMEM-43) are implicated in a variety of cancers." (PMID 34571860, 2021). "The contradictory roles of claudin-1 in different cancers reflect that different oncogenic pathways can hijack different roles of claudins to contribute to cancer progression." (PMID 34354941, 2021). "The epithelial phenotype of cancer cells is governed by claudin-1 (CLDN1), claudin-7 (CLDN7), and E-cadherin (CDH1) genes, while the mesenchymal phenotype is regulated by ZEB1, SNAI1, SNAI2, and Vimentin (VIM) genes." (PMID 33670804, 2021). "The differential expression of CLDN-1 observed in different cancers outlines the complexity of the potential role that it plays in the cancer process." (PMID 31952355, 2020). "Delocalization of CLDN-1 from the membrane to cytoplasm and nuclei of cancer cells supports cancer growth and malignancy." (PMID 31952355, 2020). "Taken together, we decipher the regulation of CLDN1 and uncovers its ability to repress cancer stemness and sensitizes chemotherapy." (PMID 32754286, 2020). "In other words, universal statements concerning CLDN-1 and cancer or CLDN-1 and barrier function are dangerous oversimplifications." (PMID 31952355, 2020). "CLDN1 is necessary to regulate physiological barrier function in various tissues, but its pathophysiological role in cancer is controversial." (PMID 32824620, 2020). "In some cancers, lower expression of CLDN-1 is shown to be associated with cancer progression and invasion, while in others, loss of CLDN-1 improves the patient survival." (PMID 31952355, 2020). "When CLDN1 is downregulated, SLUG is activated and binds the CLDN1 promoter, resulting in further downregulation of CLDN1 and the promotion of cancer progression." (PMID 32754286, 2020). "Previous studies have shown that the CLDN1 involvement in suppressing or activating metastasis is paradoxical among different cancers." (PMID 32754286, 2020). "We also found that upregulation of both RUNX3 and CLDN1 enhanced the sensitivity of cancer cells to cisplatin and induced cell death." (PMID 32754286, 2020). "A human-mouse chimeric CLDN-1 mAb (clone 3A2) demonstrated cellular cytotoxicity against CLDN-1 expressing cancer cells." (PMID 31952355, 2020). "Studies have shown that CLDN-1 is involved in the mediation of inflammatory responses initiated by TNFα in different cancers." (PMID 31952355, 2020). "Taken together, these results demonstrated that CLDN1 inhibits SLUG expression via suppression of the ERK1/2 pathway to inhibit cancer-cell migration and metastasis." (PMID 32754286, 2020). "In contrast, the histone deacetylase inhibitor trichostatin A or vorinostat facilitated CLDN1 expression in high-metastatic cancer cells and thus increased the efficacy of chemotherapy." (PMID 32754286, 2020). "For long-term observation of cancer metastasis, knockdown of SLUG abrogated the lung metastasis promoted by CLDN1 loss." (PMID 32754286, 2020). "The localization of CLDN-1 as a transmembrane protein makes it a perfect target for the enhanced drug absorption for preventing infection and treating cancer." (PMID 31952355, 2020). "A number of gene nodes linked to drug resistance in other cancer types (including CAT, TRIM59, ANXA2, ADM, AJUBA, HSPA1A/1B, LAMC2, TRIM14, KRT8, KRT18, KRT9, CLDN1, and SMARCA2) were also down-regulated in PARPis-sensitive AsPCs." (PMID 33213473, 2020). "With respect to the steps of EMT, which are essential for metastasis, the researchers of the present study studied a number of genes reported to have a role in EMT in different cancers, such as Claudin-1, Cofilin-1, AXL, and GAS6." (PMID 31700829, 2019).
cancer (continued). "Slug, a well-known zinc finger transcriptional repressor, has been reported to participate in epithelial–mesenchymal transition (EMT) and cancer metastasis by suppressing its downstream target genes (such as E-cadherin, occludin, claudin 1, and integrin α3)." (PMID 31847356, 2019). "The high expression of claudin-1 has been found in the aggressive cancer tissue, and the knockdown of claudin-1 reduced cell migration." (PMID 31404237, 2019). "Recent evidences suggest that Slug participates in epithelial-mesenchymal transition (EMT) during embryonic development and cancer metastasis by suppressing the expressions of its downstream target genes like E-cadherin, occludin, claudin-1, and integrin α3." (PMID 30612578, 2019). "In CLBC cells, DOCK1 mediates cell growth and motility through down-regulating the expression of claudin-1 via the RRP1B–DNMT–claudin-1 pathway, and claudin-1 serves as an important effector in DOCK1-mediated cancer progression and metastasis." (PMID 31717460, 2019). "Much effort has been focused on understanding CLDN1 function and regulation in cancer; however, little is known about its potential usefulness as a therapeutic target." (PMID 28659146, 2017). "Recently, the roles of CLDN1 in metastasis have received increasing attention because increased permeability of endothelial cells is required for cancer cells to intravasate and extravasate." (PMID 28757546, 2017). "Other studies found a strong CLDN1 expression at the cell–cell boundaries and in the cytoplasm of cancer cells." (PMID 28659146, 2017). "Here we propose a mechanism for this effect by which miR-30a counteracts the aggressiveness and metastasis of cancer cells by increasing tight junction molecules—CLDN-1, CLDN-2, and CLDN-3—via targeting the 3′-UTR of Slug mRNA." (PMID 26918943, 2016). "The ability of CLDN1 to affect the proliferation and colony formation of cancer cells was also detected using a CCK8 assay and a colony formation assay, respectively." (PMID 27974683, 2016). "The number of copies of CLDN1 in cancer tissues was increased significantly compared with normal cervical tissues." (PMID 27974683, 2016). "All of the results suggest that MTs of ADPGK, PCGF6, PKP2, NUP93 and SLC22A5 can be the driver mutations controlling the cancer metastasis via affecting the EMT pathways where Snail, Claudin-1 or ZEB1 is involved." (PMID 27625789, 2016). "In the CLDN1 overexpression group, metastatic cancer cells were found in the lungs of mice (5/5), but in the control group, the metastatic rate was 2/5." (PMID 27974683, 2016). "In cancer, the role of claudin 1 appears to be dichotomous; upregulated in some cancers and downregulated in others." (PMID 27649506, 2016). "In cancer, claudin 1 increased cell motility and invasiveness through its deregulation of MMPs such as MMP1, MMP-2 and MMP-9 directly." (PMID 26633531, 2015). "Such a role has implications for claudin 1 as a potential target for antibody treatment of viral diseases, as well as in cancer therapy." (PMID 26633531, 2015). "Tight junction molecules, such as CLDN1, improved invasion activity in cancer cell lines through activation of MT1-MMP-1 and MMP-2, and peak expression of claudin-4 RNA has been temporally associated with the implantation window in humans." (PMID 24564230, 2014). "In these cancers, claudin 1 mislocalization was shown to increase the invasiveness of the cancer cells." (PMID 23721519, 2013). "Their expression is altered in various cancers compared to normal tissues, and claudin-1, -3, -4 and -7 are among the most frequently dysregulated members of the claudin family." (PMID 24009024, 2013). "Altered expression of several claudin proteins, in particular claudin-1, -3, -4 and -7, has been detected in various cancers." (PMID 24009024, 2013). "The cancer-promoting role of claudin-1 via its effect on invasion or motility of cancer cells has been described in various cancers." (PMID 24009024, 2013).
cancer (continued). "Several studies have analyzed the role of claudin 1 (CLDN1) in epithelial physiology as well as in cancer development and metastasis (reviewed by Gupta and Ryan and Myal, Leygue and Blanchard)." (PMID 23844228, 2013). "Claudin 1 gene expression was significantly down regulated in all the cancer cells compared to PNT2." (PMID 24358122, 2013). "Claudin-1 is one of the most dysregulated claudins in human cancers, and its crucial role in various cancers has been described." (PMID 24009024, 2013). "In colorectal cancer (CRC), different data have been published concerning claudin-1 expression in cancer cells." (PMID 22408413, 2012). "We conclude that dystopic subcellular localizations of Snail-1 and claudin-1 may participate in changes of cellular morphology and behavior which might be associated with altered effectory pathways of proteins and thus substantially contribute to the cancer development." (PMID 22408413, 2012). "Overexpression of CLDN1 was correlated with suppression of cancer cell migration, invasion and metastasis." (PMID 20805891, 2010). "Similar to our findings, a recent study has demonstrated the nuclear localization of claudin 1 in a number of carcinoma cells." (PMID 18162136, 2007). "Among these, CLDN1, 4, 6, and 18.2 have already been utilized as targets for cancer treatment." (PMID 41461671, 2025). "The data indicate that all cases of primary CRC and CRCLM might be adaptable for CAR-T cell therapy targeting any of the three membrane-type protein cancer antigens, namely CLDN1, EphB4, and LAT1." (PMID 40806530, 2025). "CLDN1 protein can act as a regulator of cancer cell autophagy." (PMID 40687428, 2025). "We analyzed expression levels and intracellular localization of seven common cancer antigens, CLDN1, EphB4, LAT1, FOXM1, HSP105α, ROBO1, and SPARC, and human leukocyte antigen (HLA) class I via immunohistochemical staining of 85 surgical specimens from primaries and liver metastases." (PMID 40806530, 2025). "While anti-claudin treatment may suppress EMT and metastasis of tumors, several studies showed anti-EMT and anti-cancer activity of claudin-1 was demonstrated." (PMID 39458944, 2024). "CLDN1 was demonstrated to cause chemoresistance in CRC via upregulating ephrin type-A receptor 2 (EPHA2) tyrosine kinase, which enhances downstream the AKT signaling pathway, and CD44 expression, which promotes cancer stemness and chemoresistance." (PMID 38731853, 2024). "Additionally, several studies provide evidence for claudin-1 being one of the most deregulated claudins in human cancer." (PMID 38338705, 2024). "For example, a single claudin protein (such as CLDN1) may be upregulated in early-stage cancer development only to be reported downregulated in late-stage or more aggressive cancer phenotypes." (PMID 38540693, 2024). "Moreover, the CLDN1 gene is another paclitaxel-resistant gene observed in cancer cells at a high level." (PMID 39003454, 2024). "Both cases of carcinoma with medullary features had retained claudin-1 expression." (PMID 40034931, 2024). "Since then, claudin-1 has been found to be over-expressed in various types of human cancers." (PMID 37102018, 2023). "Some cancer cells aberrantly express claudin 1 in the cytoplasm." (PMID 36714681, 2023). "Claudin-1 is a well-described tight junction protein with prognostic value in many human cancers." (PMID 37102018, 2023). "These include the recent discovery of compounds which may modulate the expression of the claudins, such as claudin-1 in the colon, and consequently halt the progression of cancer." (PMID 37627123, 2023). "Beside the mentioned mechanisms, upregulated CLDN1 expression was shown to promote Notch signaling through its noncanonical role in regulating Notch/PI3K/Wnt/β-cateninSer552 signaling, which underlies the induction of colitis-associated cancer." (PMID 36672179, 2023). "Additionally, Claudin-1 is a cancer invasion/metastasis suppressor, prognostic predictor, and a potential drug." (PMID 35432533, 2022).
cancer (continued). "Increased claudin 1 was observed in cancer cells from starvation-induced autophagy." (PMID 36552443, 2022). "Currently, the principal research focus of CLDN1 is in cancer studies, including tumorigenesis and epithelial-mesenchymal transition, and it has been reported to be principally associated with the regulation of cellular functions such as cell proliferation, migration, and invasion 28-31." (PMID 35370461, 2022). "Studies have showed that CLDN1 was a double-edged sword in cancer." (PMID 34116704, 2021). "Wound healing assays for IGROV1 and SKOV8 indicated that CLDN1 knockdown resulted in delayed gap closure (paired t-test, p= 0.046 and p= 0.043, respectively), supporting an important role for CLDN1 in cancer cell migration." (PMID 33828978, 2021). "Interestingly, DNA hypermethylation of the CLDN1 promoter abrogated SLUG-mediated suppression of CLDN1 in low-metastatic cancer cells." (PMID 32754286, 2020). "Although the downregulation of CLDN1 is involved in cancer malignancy, how the expression of CLDN1 is controlled and the action mechanism of CLDN1 remain unclear." (PMID 32754286, 2020). "Likewise, the shuttling of CLDN-1 between the cell membrane, cytoplasm and nucleus is a deciding factor in the development and progression of cancers." (PMID 31952355, 2020). "Additionally, one transcription activator, RUNX3, can directly bind the CLDN1 promoter and drive CLDN1 transcription, leading to suppression of cancer progression." (PMID 32754286, 2020). "Based on our studies, CLDN1 protein level sensitizes cancer cells to chemotherapy drugs." (PMID 32754286, 2020). "CLDN1 overexpression may thus sensitize cancer cells to cisplatin by inhibiting the percentage of CSCs and enriching the percentage of cells in the G2/M phase." (PMID 32754286, 2020). "Key cancer-related transcripts were identified, such as CLDN1, TP63, FGF14, DDX60 and DRAM." (PMID 32839509, 2020). "HCC cell line experiments demonstrated the role of CLDN-1 in the process of cancer cell invasion." (PMID 31952355, 2020). "Among the claudin family, CLDN-1 is the most extensively studied protein and has been shown to be involved directly or indirectly in the development and progression of cancer, and also has a suppressive role in some cancers." (PMID 31952355, 2020). "Additionally, dysregulation of claudin-1 both increase and decrease in expression has been reported in several cancers." (PMID 32309226, 2020). "The specific role of CLDN-1 in various cancers is discussed in the following sections." (PMID 31952355, 2020). "Nuclear localization has been reported for ZO1/ZO2 and CLDN1-4 in several types of cancer cells." (PMID 32012812, 2020). "Conversely, CLDN1 overexpression sensitized cancer cells to cisplatin, carboplatin, and taxol." (PMID 32754286, 2020). "Moreover, CLDN1 expression in cancer cells is positively correlated with cancer progression because TJP is essential for cell–cell interactions that promote carcinogenesis and metastasis." (PMID 28757546, 2017). "Indeed, immunohistochemistry analyses in CRC and normal mucosa samples showed that cancer cells display a membranous or membranous/cytoskeletal staining of CLDN1." (PMID 28659146, 2017). "Claudin 1 and Claudin 7 can be used in cancer diagnosis and treatment." (PMID 28376864, 2017). "Expression of CLDN1 has been examined in a number of cancer types." (PMID 27974683, 2016). "CLDN1 expression and function are altered in cancer, including CRC." (PMID 26894861, 2016). "For inhibition of cancer cell metastasis, an induction of cell-cell adhesion (characterized by an increase of epithelial cell adhesion proteins including the tight junction proteins, ZO-1 and claudin-1) is required." (PMID 27875549, 2016). "The deregulation of CLDN1 in different cancers is not well understood." (PMID 27649506, 2016). "Moreover, claudin 1 has recently been shown to promote cancer progression and metastasis in several cancers including colon, liver and squamous cell carcinomas." (PMID 27649506, 2016).